TNF (tumor necrosis factor)
Diseases named in the same sentence as TNF in open-access papers (continued):
Sharing a sentence is not in itself a finding about the gene and the disease.
Sepsis (continued). "Meng’s group also showed that endotoxin lipopolysaccharides via TLR4 signaling pathway to activate translocation of NF-κB and further regulate expression of pro-inflammatory genes, including TNF-α, IL-6, and IL-1β during sepsis." (PMID 35370629, 2022). "Compared with control group, levels of TNF-α in plasma and lung tissues in sepsis group increased (p = 0.035, p = 0.001, respectively)." (PMID 35265263, 2022). "In contrast, menthol treatment significantly (p < 0.05) abrogated the sepsis-induced elevation in hepatic TNF-α levels." (PMID 36120368, 2022). "The blood glucose level of patients with sepsis was positively correlated with the levels of IL-6, TNF-α, and IL-1β." (PMID 35664433, 2022). "Nicotine (17.5 ± 2 mg/kg, 7 ± 0.8 mg/kg, s.c.)pretreatment reduced the mortality during the early phase of sepsis and reduced the concentrations of TNF-α, IL-1β, IL-6, and MIP-2 after 2 or 10 h of sepsis." (PMID 35251010, 2022). "In particular, proinflammatory cytokines, such as tumor necrosis factor (TNF) and interleukin (IL)-1β, were considered to play major roles in the so-called cytokine storm in acute sepsis." (PMID 36140361, 2022). "TNF-α of plasma and lung tissues increased in sepsis (p all<0.05) and decreased in sepsis+SO2 (p for lung tissue <0.05)." (PMID 35265263, 2022). "Some biological pathways were more markedly up-regulated (severe versus mild sepsis) in Neu1 than that in other neutrophil types such as hypoxia, interferon-γ response, and TNF-α signaling via NFκB." (PMID 36304125, 2022). "Regarding transcripts regulation, landiolol up-regulated the transcript of IL-1b in OVR females and potentiated the sepsis-induced increase of TNFα." (PMID 35322092, 2022). "Clinical and experimental studies have shown that the massive release of proinflammatory cytokines (IL-6 and TNF-α) can trigger sepsis-induced cardiac dysfunction, and inhibition of the expressions of IL-6 and TNF-α can significantly attenuate SIMI." (PMID 35571240, 2022). "In preclinical studies, TAK-242 showed potent suppressive effects on the production of tumor necrosis factor-α (TNF- α), interleukin-1 (IL-1) and interleukin-6 (IL-6) in both murine and porcine models of sepsis." (PMID 35456534, 2022). "Oxytocin also impedes the endotoxin-induced increases in cortisol, TNF-α, and IL-6 in a rodent model of sepsis." (PMID 35572539, 2022). "In a mouse model of lipopolysaccharide-induced sepsis, fluoxetine reduces mortality and decreases tumor necrosis factor-α (TNF-α) levels when used preventively." (PMID 36203121, 2022). "Previous studies have demonstrated that NETs can induce macrophage pyroptosis, elevate caspase-1 with increasing NETs dose, and increase inflammatory cytokines IL-1β and TNF-α in sepsis." (PMID 36430491, 2022). "When IL-6 is combined with additional sepsis markers as TNF-a and CRP, the sensitivity and NPV for diagnosing EOS improves." (PMID 35449688, 2022). "Accordingly, the elevation of TNF-α and IL-6 in serum and liver homogenates of burn sepsis mice was markedly prohibited by glutamine treatment, which was also reversed by BLZ945." (PMID 36601059, 2022). "The levels of IL-6, TNF-α, and IL-1β in the miR-221 inhibitor group were significantly lower than those in the sepsis group (P < 0.05)." (PMID 35186224, 2022). "The study found that both the ACF and HJD can inhibit the release of inflammatory factors (NO, IL-1β, IL-6, and TNF-α), reduce inflammatory cell infiltration, and induce organ damage by sepsis." (PMID 36160407, 2022). "Clinical studies have found that in patients with severe sepsis, the blood levels of TNF-α, IL-1β, IL-6, IL-8, IFN-γ, and MCP-1 are significantly increased." (PMID 35370629, 2022). "Menthol markedly suppressed sepsis induced elevation of tissue TNF-a, ameliorated sepsis-induced cleavage of caspase-3 and restored the antiapoptotic marker Bcl2." (PMID 35814769, 2022).
Sepsis (continued). "DIE also reversed the increase in tumor necrosis factor-α and nitrite levels in the serum of mice induced with sepsis." (PMID 35607518, 2022). "Further supporting our belief that targeting inflammatory pathways to minimise cytokine storm is the key to combating sepsis and lowering sepsis-related mortality is the finding that proinflammation cytokines like TNF- and IL-1 become elevated within sepsis." (PMID 36199798, 2022). "Conversely, B1a cells also produce IL-3, IL-6, IL-17, and TNF-α, which play proinflammatory roles in sepsis." (PMID 36425582, 2022). "During sepsis, these pro-inflammatory cytokines, such as tumor necrosis factor- alpha (TNF-α) and interleukins-1β (IL-1β), are able to activate endothelial cells." (PMID 36530954, 2022). "Beyond procalcitonin, other frequently studied biomarkers such as CRP, IL-6, IL-8, IL-10, and TNF-α have had much less success predicting infection and sepsis." (PMID 39604183, 2022). "Studies also showed that Wip1 expression was negatively correlated with neutrophil production of inflammatory cytokines, including TNF-α, IL-6 and IL-1β, in sepsis patients, which was mediated by the p38 MAPK-STAT1 and NF-kappaB pathways." (PMID 35538489, 2022). "Utilization of a β1-AR blocker, CaMKII inhibitor, and β1-AR agonist showed that the NE from ICA cells can active cardiac β1-AR-CaMKII signaling, which crosstalks with NF-κB and MAPK pathways to promote TNF-α production and myocardial dysfunction during sepsis." (PMID 35079095, 2022). "In the early stages of sepsis, activation of the host’s innate immune system leads to a massive release of pro-inflammatory mediators, the main ones including IL-6 and TNF-α, as well as chemokines." (PMID 36685507, 2022). "During the pathological progress of sepsis, several inflammatory cytokines such as IL‐1β, IL‐6, TNF‐α and IFN‐γ are excessively produced." (PMID 35502484, 2022). "SGB vigorously suppresses the sepsis-elicited release of inflammatory factors IL-6 and TNF-α, alleviating ALI in rats." (PMID 36333771, 2022). "During sepsis, proinflammatory cytokines, such as IL-1β/TNF-α, are responsible for structural alterations in the BBB." (PMID 35295600, 2022). "The shift to use ultralow duty cycles was supported by the finding that a single 60 s pulse applied to the cervical vagus nerve was sufficient reduced systemic serum TNF levels in a rat model of sepsis." (PMID 36478876, 2022). "Serum levels of IL-6 and TNF-α are highly elevated in newborns with sepsis compared to healthy newborns, and lower in the survivors of elderly patients with sepsis than non-survivors, indicating their relation to inflammatory syndrome of sepsis." (PMID 35167625, 2022). "In another study with mouse model of sepsis, EVs from intestinal luminal lavage were enriched with miRNAs, which putatively targeted TNF-α and IL-17A." (PMID 35187084, 2022). "Meanwhile, we have also analyzed IL-1β and TNF-α expressions in serum, both of which are pro-inflammatory factors and play a vital role in promoting sepsis." (PMID 35252164, 2022). "The release of TNFα is self-sustaining in sepsis due to autocrine secretion, as the binding of endotoxin to lipopolysaccharide (LPS)-binding protein and its subsequent transfer to CD14 on macrophages will stimulate TNFα release." (PMID 35056044, 2022). "Post-sepsis platelet transfusions also reduced plasma levels of TNF-α and IL-6 and the organ injury biomarker aspartate aminotransferase (AST)." (PMID 35192546, 2022). "Analysis of plasmatic cytokines showed that, in all mouse strains, sepsis was accompanied by increase of IL-1β, IL-6, IL-10, TNF-α and IFN-γ." (PMID 36119089, 2022). "We noted 11 common DNA binding sites in periodontitis and IL-10-stimulated neutrophils, 625 in NMOSD and TNF-α-stimulated neutrophils, and 19 in sepsis and LPS-stimulated neutrophils." (PMID 35757755, 2022).
Sepsis (continued). "These two cytokines, TNFα pro-inflammatory and IL-10 with pleiotropic effects immunity and inflammation, have also been observed to rise early in sepsis and in acute respiratory failure." (PMID 36548717, 2022). "Sepsis is characterized by the over-production of pro-inflammatory cytokines such as interleukin (IL)-1β, IL-6, IL-8, and tumor necrosis factor-α (TNF-α), which activate the host’s immune responses." (PMID 36188562, 2022). "TNF-α treatment significantly increased mRNA levels of the NF-κB p65 subunit in HUVECs, simulating the upregulated inflammation that occurs in sepsis." (PMID 35328486, 2022). "HIF-1α was shown to be a critical determinant of sepsis promoting the production of inflammatory cytokines, including TNF-α, IL-1, IL-4, IL-6, and IL-12, which reach harmful levels during early sepsis." (PMID 35682644, 2022). "It was found that TNF-α challenge elevated Mid1 expression more than 5-fold compared with unstimulated samples, indicating that endothelial cell expression of Mid1 is increased in response to both sepsis and TNF-α exposure." (PMID 36614145, 2022). "In a classic Sprague‒Dawley rat model of sepsis peritonitis, resveratrol significantly decreases LPS-induced expression of NF-κB, TNF-α, IL6, IL-1β, and TLR4 and increases the expression of p-PI3K, p-AKT, and p-mTOR in the myocardium." (PMID 36483739, 2022). "Endotoxin tolerance, measured by TNF-α production stimulated through LPS in PBMCs and splenocytes, was induced early in the sepsis model, starting from 6 h after sepsis." (PMID 35743025, 2022). "The 24-h proinflammatory cytokine levels were higher, and these data corroborate with previous results, which indicate increased concentrations of IL-1β and TNF-α early after sepsis, with a peak increase between 18 and 48 h after CLP induction." (PMID 36333747, 2022). "In a polymicrobial sepsis-induced mouse model where exogeneous cGMP was administered to increase cGMP bioavailability, plasma levels of IL-6 and TNF-α are substantially reduced, and ODQ (an inhibitor of soluble GCs) showed the opposite effect." (PMID 35269704, 2022). "IL-6 and TNF-α represent potent proinflammatory cytokines which correlate with increased mortality and morbidity in recent studies of pediatric and adult sepsis." (PMID 36733389, 2022). "CLP-induced sepsis can produce inflammatory mediators including IL-6, TNF-α, and IL-1β, which aggravate inflammation." (PMID 35979014, 2022). "TNF-α response after LPS stimulation in PBMCs was significantly decreased until 48 h after sepsis, approximately 0.1% of the sham group, and then started to recover." (PMID 35743025, 2022). "Liu-Shen-Wan protects against sepsis by lowering plasma levels of tumor necrosis factor-α (TNF-α) and malondialdehyde (MDA) and enhancing the phagocytic capability of peritoneal macrophages." (PMID 36408247, 2022). "TNF-α is accumulated in many pathological conditions, including sepsis, malignant tumors, heart failure, and chronic inflammatory diseases." (PMID 36110326, 2022). "Under the state of sepsis, the activation of the monocyte-macrophage and complement systems is induced, triggering the excessive release of inflammatory mediators, such as TNF-α, IL-1, IL-8, bradykinin, and histamine." (PMID 35081868, 2022). "LPS-stimulated Lcn2-/- mice also exhibit elevated hallmarks of sepsis, including the expression of proinflammatory cytokines such as TNF-α and IL-18, immune cell apoptosis, and systemic organ dysfunction." (PMID 36054235, 2022). "It is a serine protease that it is detectable within a few hours in sepsis experimental models obtained after the infusion of tumor necrosis factor and endotoxins." (PMID 35884956, 2022). "We dosed TNF-α as it is one of the master regulators of inflammation and a primary mediator of systemic response in sepsis and infections." (PMID 36287942, 2022).
Sepsis (continued). "Exposure to inflammatory stimuli, including TNF-α and endotoxin, as well as inflammatory states such as sepsis, degrade the glycocalyx by triggering release or activity of various enzymes and/or reactive oxygen species (ROS)." (PMID 35872762, 2022). "The systemic inflammatory response of sepsis leads to the release of a number of proinflammatory mediators such as IL-6 and TNF-α, which induce the production of cytokine signaling inhibitors." (PMID 35719361, 2022). "As expected, such changes ultimately led to proinflammatory cytokine production during late-stage sepsis (IL-1β, IL-6, IFNγ, TNFα)." (PMID 35349828, 2022). "Among these factors, TNF-α plays a key role in the pathogenesis of sepsis, and IL-1β and IL-6 participate in the initiation of the sepsis cascade and reflect the degree of inflammation." (PMID 35576220, 2022). "We have also observed that intraperitoneal injection of eMSC in rodent models of sepsis reduced serum levels of TNFα, confirming that eMSC act a distance (unpublished observations)." (PMID 36551231, 2022). "TNF-α can induce the expression of IL-6, IL-10, and IL-18, which can be used as an inflammatory marker for the development of sepsis." (PMID 35698642, 2022). "Cytokines (especially TNF-α) and LPS from sepsis upregulated miR370-3p in the brain, at least in part, facilitated encephalopathy through an alteration of energy status in neuron cells." (PMID 35628259, 2022). "In various animal models of sepsis, IL-6 and TNF-α expression were significantly elevated compared to the normal group." (PMID 36685507, 2022). "Promote the release of pro-inflammatory factors TNF-α, IL-6, IL-1β, the occurrence of inflammatory response mediates organ damage, increase the mortality of sepsis." (PMID 35463634, 2022). "We found that after the administration of HIF 1a, inflammatory factors TNF a and IL-6 decreased compared with the sepsis group." (PMID 36569834, 2022). "During sepsis, the expression levels of proinflammatory cytokines, such as TNF, IL-6 and IL-1β, are increased in the central nervous system (CNS), which is believed to play a pivotal role in long-term cognitive impairment after sepsis." (PMID 35883093, 2022). "Our data disagree with those of previous studies of LPS-induced sepsis that found decreased plasma concentrations of IL-6, TNF-α, and MIP-2 in mice treated with riboflavin 6 h after LPS injection (14-, 16)." (PMID 35648977, 2022). "The levels of IL-6, TNF-α, and IL-1β in the HECTD2siRNA group were significantly lower than those in the sepsis group (P < 0.05)." (PMID 35186224, 2022). "IL-1β, TNF-α, IL-10 and IL-6 are pro-inflammatory cytokines that play core roles in the pathogenesis of sepsis." (PMID 35225146, 2022). "During sepsis, elevated cytokines (tumor necrosis factor-alpha, interleukin-6, interleukin 1 beta) alters sympathovagal balance." (PMID 35572539, 2022). "It reduces the level of inflammatory factors such as TNF-α and IL-1β produced by macrophages, and increases the level of macrophages derived anti-inflammatory factor IL-10, functioning protective role in sepsis." (PMID 35463634, 2022). "For example, acquisition of a so-called “endotoxin tolerant” phenotype in monocytes derived from patients with sepsis or acute respiratory distress syndrome is marked by reduced TNFα production in response to ex vivo stimulation with LPS22–24." (PMID 36402888, 2022). "The circulating TNF levels of approximately 60 pg/ml in sepsis patients is orders of magnitude below concentrations easily tolerated by humans following injection of recombinant TNF (Section 3)." (PMID 35814227, 2022). "Several anti-TNF-α agents, e.g., monoclonal anti-TNF-α antibody, have been developed and their therapeutic effects on improving survival in sepsis patients have also been reported." (PMID 35337084, 2022). "We found that the γ3-RBCNPs target human umbilical vein endothelial cells (HUVECs) activated by TNF-α in vitro and the infected lung of mice in the sepsis model very well." (PMID 35783411, 2022).
Sepsis (continued). "VNP20009 is an attenuated engineered S. Typhimurium with purI and msbB gene deletion, 108-kb deletion, and many single nucleotide polymorphisms (SNPs) with increased tumor chemotaxis and lowered tumor necrosis factor α (TNF-α)-induced sepsis." (PMID 35847095, 2022). "In this regard, in vitro exposition of eGC to endotoxin, TNFα, Angiopoietin-2, or thrombin (all molecules released during sepsis) induced eGC damage." (PMID 36613805, 2022). "Considering severe sepsis, the anti-tumor necrosis factor alpha (TNF-α) agent, etanercept, was used to replace tacrolimus and corticosteroid." (PMID 36059444, 2022). "Production of proinflammatory cues including IL1, IL6, IL8, TNF, and MIP1a is a key driver of morbidity during sepsis." (PMID 35166205, 2022). "Inflammatory mediators such as the pro-inflammatory cytokines IL-1β, TNFα, and IFNγ, secreted during sepsis, have been shown to induce chemerin expression in adipocytes as well as other cells." (PMID 35204801, 2022). "On the contrary, miR-483-5p and miR-497-5p resulted in aggravating pulmonary disease induced by sepsis since their overexpression determined an increased production of TNFα, IL1β and IL6, thus promoting inflammation." (PMID 36012630, 2022). "With its extrication into circulation in the early phase of sepsis, TNF-α can in turn escalate the systemic inflammatory response." (PMID 35337084, 2022). "Specifically, TNF-alpha is one of the best studied cytokines in sepsis, being able to stimulate the expression of a wide variety of genes involving the myocardium and the surrounding tissue environment." (PMID 36551850, 2022). "In LPS-induced sepsis mice, lncRNA-HOTAIR reduced TNF-α expression by suppressing the activation of NF-кB signaling, indicating the involvement of NF-кB signaling in sepsis." (PMID 35048778, 2022). "Several reports have shown that TNF-α, IL-6, and IL-10 can be used as criteria for evaluating the severity of sepsis, and that elevated levels of cytokines predict mortality in septic mice." (PMID 36743669, 2022). "Twenty-four hours after LPS injection, mice presented characteristic symptoms of sepsis: diarrhea, malaise and piloerection, and elevated plasma TNF-α and IL-6 levels." (PMID 36330522, 2022). "The administration of Rg4 reduced cytokine levels, including TNF-α, IL-1β, and NO in the kidneys, the most sensitive organ to sepsis resulting from high-grade CLP." (PMID 36142743, 2022). "Sepsis induced a significant increase in the mRNA levels of the inflammatory marker IL-6 (p < 0.05) whereas the gene expression of TNF-α and IL-1β was reduced (p < 0.01 and p < 0.05, respectively)." (PMID 35795581, 2022). "The expressions of MCP-1 and TNF-α in GG genotypes in T2DM with sepsis group were significantly higher than AA or GA genotypes (P < .05)." (PMID 35960063, 2022). "Plasma TNFα was increased by sepsis in all groups (p ≤ 0.0001, vs healthy controls) similar to placebo (p ≥ 0.07)." (PMID 35732826, 2022). "In conclusion, upregulation of miR370-3p in sepsis encephalopathy was a result of the activation by sepsis molecules (LPS and TNF-α) which was attenuated by BAM15 along with decreased organ damage through BAM-15-induced anti-inflammatory macrophages." (PMID 35628259, 2022). "Some studies have shown that paeoniflorin inhibited the levels of TNF-α both in sepsis model rats in vivo and RAW264.7 cells in vitro." (PMID 35445094, 2022). "As compared to the baseline, plasma TNF-α concentration peaked at 6 h after sepsis induction, and this significant elevation persisted during the entire period of invasive hemodynamic monitoring in the septic shock subgroup." (PMID 35615093, 2022). "In parallel, for the sepsis parameters, serum TNF-α, IL-1β, IL-6, IL-8, endotoxemia, and blood-bacteria-free DNA in severe cases were higher than other groups and most of the levels of these parameters were different between COVID-19 severities." (PMID 35406667, 2022).